LMX1B (LIM homeobox transcription factor 1 beta)
Diseases named in the same sentence as LMX1B in open-access papers (continued):
Sharing a sentence is not in itself a finding about the gene and the disease.
glomerular disease (4 papers, 2007 to 2024). "LMX1B gene mutations are associated with autosomal dominant nail-patella syndrome, a condition displaying dysplastic nails, hypoplastic patellae, and glomerulopathy with proteinuria and hematuria." (PMID 21904677, 2011). "Mutations of the human Lmx-1b gene are responsible for the nail-patella syndrome, an autosomal dominant disease with skeletal abnormalities, frequently associated with glomerulopathy." (PMID 21904677, 2011). "Recent immunohistological studies in NPS patients with severe glomerular disease suggest a possible regulation of type III collagen by LMX1B, while the homozygous mutations of LMX1B do not appear to dramatically affect the expression of type IV collagen chains and podocin in NPS patients." (PMID 17515884, 2007).
kidney failure (4 papers, 2009 to 2016). An acute or chronic condition that is characterized by the inability of the kidneys to adequately filter the blood. "Mice with one normal and one copy of Lmx1b with the Icst mutation have eye defects and some die shortly after birth probably due to kidney failure." (PMID 24809698, 2014). "We considered a possible cause of death to be kidney failure because of the importance of LMX1B in podocyte and slit diaphragm development." (PMID 24809698, 2014). "In support of the role of LDB1 in LMX1B function, in mice specific inactivation of Ldb1 in podocytes leads to gradual loss of foot processes and GBM defects are found which lead to renal failure." (PMID 24809698, 2014). "A recent study of a podocyte-specific Lmx1b knockout (using a Cre-Lox system based on the NPHS2 promoter) showed later development of proteinuria and greater expression of type IV collagen chains and podocin, although the animals still died of kidney failure within 14 days." (PMID 18535845, 2009).
breast carcinoma (3 papers, 2022 to 2024). "We identified a novel candidate gene at a breast cancer GWAS locus where a milk eQTL that increased expression of LMX1B was associated with increased cancer risk." (PMID 39265573, 2024). "For example, combining our milk eQTLs with breast cancer GWAS summary statistics, we provide the first functional evidence connecting LMX1B expression to a nearby breast cancer GWAS locus." (PMID 39265573, 2024). "We developed a multiplex digital droplet polymerase chain reaction (ddPCR) assay for the detection of ctDNA in breast cancer patients that targets a combination of two methylations specific for breast tissue (LMX1B and ZNF296) and one cancer specific methylation (HOXA9)." (PMID 37225860, 2023). "Using mRNA sequencing and proteomic data from TCGA and CPTAC of 24 different solid tumors, we identified six potential genes that are specifically upregulated in breast carcinoma: NAT1, MGP, SCGB2A2, LMX1B, TFAP2B, and TRPS1." (PMID 36284362, 2022).
nail-patella-like renal disease (3 papers, 2017 to 2024). A severe nephropathy characterized by renal dysfunction, proteinuria, edema and microscopic haematuria. "Recently, a missense mutation (R246Q) in LMX1B was reported as a cause of glomerular pathologies without extra-renal manifestations, otherwise known as nail patella-like renal disease (NPLRD)." (PMID 28059119, 2017).
nephrotic syndrome (3 papers, 2005 to 2024). A collection of symptoms that include severe edema, proteinuria, and hypoalbuminemia; it is indicative of renal dysfunction. "Mutations in NPHS2, which codes for podocin, and LIM homeobox transcription factor 1 Beta (LMX1B), a regulator of podocin expression, have been found to cause nephrotic syndrome." (PMID 32708597, 2020).
schizophrenia (3 papers, 2011 to 2017). A major psychotic disorder characterized by abnormalities in the perception or expression of reality. "Interestingly, three SNIPs in LMX1 A and one in LMX1B were found associated with schizophrenia, and were the same as those previously identified in PD42." (PMID 29038581, 2017).
chronic kidney disease (2 papers, 2021 to 2023). Impairment of the renal function secondary to chronic kidney damage persisting for three or more months. "The LMX1B variant was de novo, whereas the PAX2 variant was inherited from the mother, who had bilateral renal hypoplasia and mild chronic kidney disease." (PMID 36835576, 2023).
diabetes (2 papers, 2020 to 2021). "We found no significant changes in levels of mRNAs encoding TH, the transcription factors nuclear receptor‐related 1 protein (Nurr1) and LIM homeobox transcription factor 1 beta (Lmxb1), or the dopamine D2 autoreceptors, indicating that diabetes per se did not affect the integrity of these neurons." (PMID 32666590, 2020).
glioma (2 papers, 2022 to 2024). A benign or malignant brain and spinal cord tumor that arises from glial cells (astrocytes, oligodendrocytes, ependymal cells). "Research demonstrated SNHG3's role in glioma by promoting tumorigenesis through miR-485-5p sequestration, leading to increased LMX1B expression and facilitating glioma cell proliferation, migration, and invasion." (PMID 39349640, 2024). "Therefore, we investigated the upstream regulator of circGFRA1 in PCa cells showing that circGFRA1 is regulated by LMX1B, which has previously been shown to be involved in many cancers, including ovarian, esophageal, and glioma." (PMID 35832649, 2022).
osteoarthritis (2 papers, 2022 to 2024). A noninflammatory degenerative joint disease occurring chiefly in older persons, characterized by degeneration of the articular cartilage, hypertrophy of bone at the margins and changes in the synovial membrane. "In the current study, we determined the specific role of LMX1B on cell apoptosis and inflammatory response in IL-1β-induced human osteoarthritis chondrocytes." (PMID 36133743, 2022). "Secondly, we observed that LMX1B silence promoted cell survival and proliferation and suppressed cell apoptosis and inflammatory response in IL-1β-induced human osteoarthritis chondrocytes." (PMID 36133743, 2022). "However, the specific role and molecular mechanism of LMX1B in IL-1β-induced human osteoarthritis chondrocytes are poorly understood." (PMID 36133743, 2022). "Some of the musculoskeletal manifestations observed in NPS are common in RA, while knockdown of LMX1B has been reported to have a protective effect on osteoarthritis, and a genetic link between LMX1B and RA has not been reported." (PMID 38355529, 2024).
ovarian carcinoma (2 papers, 2020 to 2022). A malignant neoplasm originating from the surface ovarian epithelium. "High expression of LMX1B was associated with decreased overall survival in patients with ovarian cancer." (PMID 33488950, 2020). "LMX1B (LIM homeobox transcription factor 1 beta) was reported as an oncogene in human ovarian cancer based on the correlation between its increased expressions with poor outcome." (PMID 36338962, 2022). "The overexpression of LMX1B in ovarian cancer cell lines increases the expression of NF-kB pathway members." (PMID 33488950, 2020). "High expression of LMX1B at mRNA levels was observed in 46% of (7/15) human ovarian cancer cell lines compared to normal OSE cell line T29." (PMID 33488950, 2020). "Functional studies revealed that the induced expression of LMX1B in both mouse and human ovarian cancer cell lines markedly increased the migration of the cells." (PMID 33488950, 2020). "Hence NF-kB pathway inhibitors might potentially affect LMX1B function in promoting ovarian cancer, which needs to be thoroughly evaluated." (PMID 33488950, 2020). "Multiple LIM domain genes, such as LMX1B and PDLIM4 contributed to the tumorigenesis of ovarian cancer." (PMID 36338962, 2022).
apneic episodes (1 paper, 2023).
Ataxia (1 paper, 2025). Ataxia refers to impaired coordination of voluntary muscle movement. "Double-mutant Lmx1b/Lmx1a mice do not develop a cerebellum, a condition associated with ataxia." (PMID 40170168, 2025).
clubfoot (1 paper, 2024). The most common congenital deformation of the foot, occurring in 1 of 1,000 live births. "This study revealed a likely pathogenic LMX1B variant, NM_002316.4: c.723_726delinsC (p.Ser242del), in Japanese twins with clubfoot." (PMID 38424113, 2024).
cyst (1 paper, 2024). A sac-like closed membranous structure that may be empty or contain fluid or amorphous material. "In the present study, we discovered that key TFs such as LMX1B and TBX10, which play critical roles in cell differentiation and organ development, are significantly down-regulated in the cyst stage of T. rubra." (PMID 39009560, 2024).
genitopatellar syndrome (1 paper, 2016). "The presence of ovotestis was described in a 46,XY girl, with the 9q33.3‐q34.1 deletion encompassing NR5A1 and LMX1B genes causing genitopatellar syndrome associated with female external genitalia and clitoromegaly." (PMID 28033660, 2016).
Lissencephaly (1 paper, 2019). A spectrum of malformations of cortical development caused by insufficient neuronal migration that subsumes the terms agyria, pachygyria and subcortical band heterotopia. "Thus, Lmx1a and Lmx1b function redundantly to maintain lissencephaly in the mouse, and simultaneous loss of these genes is sufficient to induce gyrification of the mouse cortex." (PMID 31729356, 2019).
mental disorder (1 paper, 2011). A disease that has its basis in the disruption of mental process. "The use of Lmx1b iCKO mice circumvents these complications by allowing the brain to develop normally through to adulthood, and they serve as a new mouse model to study mental disorders associated with central 5-HT deficiency." (PMID 21246047, 2011).
mood disorder (1 paper, 2025). A cognitive disorder a disturbance in which the person's mood is hypothesized to be the main underlying feature. "Dysregulation of LMX1B increases pain sensitivity and mood disorder risk, while ESR2 affects pain thresholds and mood via estrogen signaling, underscoring their role in the complex interplay of pain and mood regulation." (PMID 40313396, 2025).
nephrosis (1 paper, 2025). Pathological processes of the KIDNEY without inflammatory or neoplastic components. "An alternative mechanism for retinal neovascularization is suggested by animal studies showing that variants in LMX1B affect collagen expression in the glomerular basement membrane, likely contributing to the renal pathology and nephrosis in NPS." (PMID 40271081, 2025).
respiratory depression (1 paper, 2022). A decrease in ventilation secondary to impaired signals from the central nervous system. "Intersectional genetic targeting methods should allow investigators to determine whether the Lmx1b neurons expressing Foxp2 (KF) or Calca (PB) contribute to opioid‐induced respiratory depression." (PMID 35134251, 2022).
retinal ischemia (1 paper, 2025). A ischemic disease that involves the retina. "One possibility is that disruptions in the LMX1B gene could result in abnormal vascular development, leading to retinal ischemia and subsequent neovascularization." (PMID 40271081, 2025).
cancer (8 papers, 2018 to 2024). A tumor composed of atypical neoplastic, often pleomorphic cells that invade other tissues. "It is reported that LMX1B was involved in organ and extremity development, including limb, kidney, brain, eye, glomerular basement membrane, and neuron; moreover, LMX1B has been shown implicated in cancer development." (PMID 36133743, 2022). "We developed a multiplex ctDNA ddPCR assay including two breast tissue specific (LMX1B and ZNF296) and one cancer specific target (HOXA9)." (PMID 37225860, 2023). "We developed a multiplex ddPCR assay targeting ctDNA with a methylation signature specific for breast tissue (LMX1B and ZNF296) and one general marker of cancer (HOXA9)." (PMID 37225860, 2023).
tumor (5 papers, 2019 to 2025). "After loss of Sox2, LMX1A and Ki-67 expression was greatly reduced, whereas the expression of LMX1B was abolished in Sox2-deficient CP tumor cells from Lcre;NICD1;Sox2cko embryos." (PMID 40128799, 2025). "Conversely, Sox2 loss resulted in significantly reduced LMX1A expression, whereas LMX1B was lost in Sox2-deficient tumor cells after birth." (PMID 40128799, 2025). "Consistently, RT-qPCR and RNA-seq studies using tumor bulk showed significantly increased Lmx1a and Lmx1b expression, along with increased Sox2 levels, compared to wild-type CP from birth to adult stage." (PMID 40128799, 2025). "In agreement, knockdown of Sox2 markedly decreased LMX1A and LMX1B expression in NOTCH-driven CP tumor cells." (PMID 40128799, 2025). "Immunofluorescence revealed a significant decrease in LMX1B expression in tumor cells following RIN-1 treatment." (PMID 40128799, 2025). "Consistently, SOX2 maintains progenitor identity through regulating their expression in CP tumors and during development, whereas LMX1A and LMX1B support SOX2 functions in tumor cell proliferation." (PMID 40128799, 2025). "Tumor cell groups were assigned based on chromatin accessibility of genes expressed in tumor cells, including Hes5 and Sox2, whereas regulatory regions of Lmx1a and Lmx1b were accessible only in tumor cell groups." (PMID 40128799, 2025). "Together, these results indicate that LMX1A and LMX1B act downstream of SOX2 to support tumor cell proliferation, whereas NOTCH inhibition suppresses SOX2-LMX1 signaling in CP tumor cells." (PMID 40128799, 2025). "Knockdown of Lmx1a and/or Lmx1b dramatically decreased Ki-67 expression in tumor cells, indicating that LMX1A and LMX1B are required for tumor cell proliferation." (PMID 40128799, 2025). "We also found that LMX1B, whose expression was inversely correlated with hsa-miR-206 expression, was a putative target gene of hsa-miR-206 and LMX1B was likely to serve as a tumor suppressor in PTC." (PMID 35342753, 2022). "We discovered that hsa-miR-206b might be involved in promoting TNM staging in PTC via targeting of LMX1B, which is a tumor suppressor in PTC." (PMID 35342753, 2022). "In agreement, SOX2 is critical in regulating the expression of LMX1A and LMX1B in tumor cells as well as progenitors in the rhombic lip, whereas LMX1A and LMX1B mediate SOX2 functions in tumor cells." (PMID 40128799, 2025). "At protein level, the expression of LMX1A, LMX1B, and SOX2 was markedly elevated in tumor cells." (PMID 40128799, 2025). "However, Sox2 knockdown failed to reduce Ki-67 expression in tumor cells with virus-mediated overexpression of LMX1A or LMX1B, suggesting that LMX1 transcription factors support NOTCH-driven CP tumor cell proliferation in the absence of SOX2." (PMID 40128799, 2025).
infection (2 papers, 2014 to 2017). The state of being infected such as from the introduction of a foreign agent such as serum, vaccine, antigenic substance or organism. "The infection was verified by immunoblot analysis for myc-tag expression and quantification of LMX1B mRNA levels in LMX1B-overexpressing podocytes." (PMID 28059119, 2017).
neurological disorders (1 paper, 2022). "Lmx1a and Lmx1b have been closely associated with neurological disorders, and it is important to know their exact role in maintaining vmDA neurons." (PMID 35269474, 2022).
LMX1B also shares sentences with these, for which no sentence is quoted: Nail dysplasia (4 papers); ocular hypertension (3); renal failure (3); Alport syndrome (2); autism spectrum disorder (2); Fabry disease (2); focal segmental glomerulosclerosis (2); glomerulopathy (2); neurodevelopmental disorder (2); Pierson syndrome (2); anterior segment dysgenesis (1); attention deficit-hyperactivity disorder (1); atypical hemolytic-uremic syndrome (1); autosomal dominant disease (1); bone disorder (1); cataract (1); central obesity (1); corneal disorder (1); craniosynostosis (1); Currarino syndrome (1); Dent disease (1); end-stage renal disease (1); ependymoma (1); fibromyalgia (1); Galloway-Mowat syndrome (1); hand-foot-genital syndrome (1); Huntington disease (1); Hyperglycemia (1); hypoplastic patellae (1); Lowe syndrome (1).
A further 17 diseases each share a sentence with LMX1B in 1 paper.